LINC00216 (long independently transcribed non-coding RNA 216)
Synonyms: PRO1617; C14orf107; NCRNA00216
Gene: Long non-coding RNA gene on chromosome 14 (58,288,033 to 58,289,158, forward strand). Ensembl gene ENSG00000279636.
Diseases named in the same sentence as LINC00216 in open-access papers:
LINC00216 is named in the same sentence as 1 disease in open-access papers, as found by Europe PMC text mining. Sharing a sentence is not in itself a finding about the gene and the disease. The quoted sentences say what the papers report.
tumour (1 paper, 2017). "In conclusion, our study identifies linc00216 as a novel tumour suppressor in GC." (PMID 27878953, 2017).